IL4 (interleukin 4)
Diseases named in the same sentence as IL4 in open-access papers (continued):
Sharing a sentence is not in itself a finding about the gene and the disease.
Allergy (continued). "In order to clarify the role of CD4+ and CD8+ T cells in the process of allergic disease caused by MP infection, we used intracellular cytokine staining combined with cell surface marker analysis to reveal if an increase in IL-4 production for MPP was associated with elevated IgE." (PMID 24977240, 2014). "IL-4 is associated with allergic response and promotes the synthesis of IgE." (PMID 21298010, 2011). "Studies regarding DNA methylation changes in cytokine genes such as interferon gamma (IFN-γ), interleukin-4 (IL-4) and IL-5 and in Forkhead box P3 (FoxP3) indicate that changes in DNA methylation may predispose IgE-mediated food sensitization or allergy in early childhood." (PMID 36756279, 2023). "Interestingly, a multi-stage genome-wide association study conducted on infantile eczema followed by childhood AA, including 2428 cases and 17,034 controls, reported significant susceptibility loci for this characteristic pattern of allergic disease, including IL4/KIF3A (5q31.1)." (PMID 36675006, 2023). "Thus, basophils might represent an important source of Th2-like cytokines (IL-4 and IL-13) in the lung microenvironment, particularly that associated with human allergic disease." (PMID 36578500, 2022). "Thus, it is not surprising that IL-4Rα is involved in the etiology of pancreatic cancer as a risk factor, where a variant of IL-4 (G3017T) might influence the risk of pancreatic cancer development according to the presence of allergies." (PMID 33804263, 2021). "IgE is the immunoglobulin paradigm of allergy, with IL-4 and IL-13 as the main stimulators of IgE production." (PMID 41596388, 2026). "The M2a subtype synthesizes cytokines such as IL-4, IL-10, and IL-13, playing a role in allergies, anti-inflammatory activity, and the induction of fibrosis." (PMID 41499529, 2026). "The hallmarks of allergic diseases are Type 2 immunity, including IL-4 and IL-13 production, IgE antibody generation, mast cell and basophil activation, histamine release, and eosinophil activation." (PMID 42274577, 2026). "In a type I hypersensitivity allergic reaction, there is a Th2 immune response characterized by Th2 cells, eosinophils, basophils, IgE, IL-4, IL-5, and IL-13 serum elevation." (PMID 41596388, 2026). "If AA is a type I hypersensitivity allergic reaction, we would therefore expect that Th2 cells, eosinophils, basophils, IL-4, IL-5, IL-13, and IgE blood concentrations rise in APA, but not in AGA or the appendectomy negative group." (PMID 41596388, 2026). "Human interleukin-4 (IL-4) is a critical therapeutic target for allergic diseases and cancer, yet current biologics face stability and specificity limitations." (PMID 41915862, 2026). "Their primary function in allergy is to facilitate the expression of IgE in germinal centers (GCs) of B cells through the expression of IL-4, thereby contributing to the initiation and progression of allergic diseases." (PMID 40427088, 2025). "In order to examine their potential relevance to allergy and immunology, serum interleukin (IL)-4, IL-4 receptor, histamine, and histamine-releasing factor (HRF) were measured by ELISA." (PMID 39941611, 2025). "The results showed that Lp synergistic FOS significantly decreased clinical allergy scores, inhibited specific antibodies (IgE, IgG, and IgG1), IL-4, IL-6, and IL-17A levels, and increased IFN-γ and IL-10 levels." (PMID 39796399, 2025). "Specific Tfh13 cells, CXCR5+BCL6+GATA3+ cells producing, not only IL-4, but also IL-13, are involved in guiding B cell isotype switching to high affinity IgE in allergy to peanut and milk." (PMID 40574856, 2025). "TFH cell subsets and functional molecules (primarily IL-4 and IL-21) play critical roles in the occurrence, progression, and maintenance of allergic diseases." (PMID 39822282, 2025). "Cytokines involved in allergic inflammation, such as interleukin-4 (IL-4) and interleukin-13 (IL-13), play significant roles in driving the immune responses characteristic of allergic diseases." (PMID 40566616, 2025).
Allergy (continued). "Emerging therapies include recombinant cytokines, exosomes, and monoclonal antibodies targeting IL-4/IL-13 or IL-5, which are mostly approved for the treatment of allergic diseases." (PMID 41007770, 2025). "This has been extensively studied in the expression of IL-4, a key cytokine in allergic disease, and the epigenetic regulation of its promoter in the context of maternal peanut allergy." (PMID 40004029, 2025). "NK cells proliferate in the presence of IL-4 and can contribute to the production of IL-4, IL-5, and IL-13 cytokines in an allergic reaction." (PMID 40718495, 2025). "Because IL-4 signaling is involved in the essential steps of the development and evolution of allergic diseases, blocking IL-4 signaling is regarded as an ideal target for the prevention and treatment of allergic diseases." (PMID 40561016, 2025). "BACKGROUND: Dupilumab, a human monoclonal immunoglobulin G (IgG) antibody that targets the IL-4 and IL-13 receptors, is used to treat various allergic diseases." (PMID 41057788, 2025). "When an allergic reaction occurred, Th2 cells secreted IL-4, which increased the concentration of IgE antibodies in the serum." (PMID 41155390, 2025). "Th2 cells secrete proinflammatory cytokines, including IL-4, IL-13, IL-5, and IL-19, which amplify the inflammatory response and recruit effector cells responsible for releasing mediators of the allergic reaction." (PMID 41002407, 2025). "ILC2s and Th2 cells secrete IL-4, IL-5, and IL-13, which induce an inflammatory immune response that plays a key role in allergic reactions." (PMID 40290033, 2025). "Based on our results, cAM-MSCs effectively reduced IL-4, a major cytokine from Th2 cells, and suppressed the activation of mast cells during early allergic reactions." (PMID 40011929, 2025). "A multigene and fate-reporter system demonstrated that the shift from Foxp3 Tregs to exFoxp3 (Th2) is IL-4-dependent during Heligmosomoides polygyrus infection and allergy." (PMID 39483462, 2024). "Dupilimab, also a mAb, allosterically inhibits IL4 and IL13, two TH2 cytokines that are implicated in allergy and IgE-mediated immune responses." (PMID 39493746, 2024). "IL-4 has been suggested to be highly expressed in autoimmune diseases and, therefore, manipulating the effects of IL-4 offers good outcomes for immune-driven diseases such as allergy and cancer." (PMID 39481080, 2024). "The IL-4, IL-5, and IL-13 secreted by Th2 inhibit the activity of Th1 and stimulate B cells to produce IgG1 and IgE, and their secretion regulates the allergy-mediated Th1–Th2 balance, lymphocyte infiltration, and cytokine secretion." (PMID 38674852, 2024). "IFN-γ promotes cellular immunity against intracellular infections, whereas IL-4 promotes humoral immunity and allergy responses." (PMID 38794167, 2024). "At the same time, IL-1β, IL-4, and IL-17 levels were reduced, demonstrating the immunosuppressive nature of cancer patients and a lower occurrence of allergies." (PMID 38951583, 2024). "The results reveal that the ratio of IFN-γ/IL-4 of RBL-2H3 cells in the allergy model group was 46.70, while the ratio in the control group was 61.78." (PMID 38397537, 2024). "The AR response include high amounts of specific IgE in the serum, high amounts of allergy relative mediators (eosinophil peroxidase and tryptase), and Th2 cytokines (IL-4, IL-5, IL-13) in nasal secretions, and high total nasal symptom scores (TNSS)." (PMID 38783329, 2024). "The desensitization phase aims to limit allergic reactions by inducing allergen tolerance through a reduction in the Th2/Th1 ratio, concomitant with a reduction in Th2-cytokines, such as IL-4." (PMID 39729447, 2024). "Since IL-4 and IL-13 play important roles in the pathogenesis of allergic diseases, blocking both the IL-4 and IL-13 signals is a powerful and effective strategy for treating allergic diseases." (PMID 38731893, 2024).
Allergy (continued). "Periostin has recently emerged as a promising biomarker of type 2 inflammation in allergic diseases, notably induced by signature type 2 cytokines like IL-4 and IL-13 or exacerbating their effects, thereby propagating allergic skin inflammation." (PMID 39722037, 2024). "The occurrence of an allergic response can stimulate the release of type 2 inflammatory mediators, including IL-4, IL-5, and IL-13, which promote the recruitment and activation of eosinophils, mast cells, and basophils, thereby inducing nasal eosinophilia." (PMID 38070374, 2024). "Recently, type 2 innate lymphoid cells (ILC2) have also been identified as one of the major producers of IL-4 and IL-13 in the development of allergic diseases." (PMID 39567378, 2024). "Th2 cells directly trigger the aggregation and activation of inflammatory cells by releasing IL-4, IL-5, IL-13, and other cytokines, and promote the occurrence of delayed airway allergic reactions." (PMID 38546350, 2024). "The cytokine IL-4 can promote the proliferation and differentiation of B cells and stimulate them to produce IgE antibodies, which is especially important in allergic reactions and anti-parasitic immunity." (PMID 39409019, 2024). "Similar to human allergic disease, canine allergy is characterized by increased expression of the type 2 cytokines IL-4, IL-5 and IL-13, e.g. in dogs with atopic dermatitis." (PMID 38835756, 2024). "TMPRSS2 reduces the recognition of viruses through human defense mechanisms; however, type 2 inflammation, in which interleukin (IL)-4, IL-5, and IL-3 are important inflammatory factors, acts as the inflammatory basis of allergic diseases in children." (PMID 38646512, 2024). "For example, oral immunotherapy (OIT) with ovalbumin suppressed allergic reactions in diarrhea-allergic mice by increasing the Treg population, which suppressed allergen-specific IgE, basophil cells, MCs, and IL-4-produced by MCs." (PMID 39729447, 2024). "In the present study, the sensitization of mice from both natural and IVF conception resulted in allergic reactions represented by higher serum levels of IgE and IL-4, as well as increased weights of the spleen and lungs." (PMID 39684703, 2024). "Th2 cells induce the secretion of cytokines such as IL-4, IL-5, and IL-13, promoting the production of immunoglobulin (Ig) A and Ig E, thereby regulating humoral immune responses and allergic diseases." (PMID 39664894, 2024). "When an allergic reaction occurs, Th2 cells release IL-4, leading to an elevation in the concentration of IgE antibodies in the bloodstream." (PMID 38534759, 2024). "The type‐2 response entails the generation of Th2 cytokines, like IL‐4, IL‐5, and IL‐13, which trigger the production of non‐opsonizing antibodies and allergic reactions, while also suppressing the pronounced inflammatory response induced by Th1 cytokines." (PMID 38774871, 2024). "cTh2 cells mainly express IL-4 and IL-13, thereby promoting the B-cell class switch to IgE antibody-producing plasma cells in type I allergic reactions." (PMID 39076967, 2024). "Despite the Th2 bias of both CME and PN allergies, IL-4-mediated regulation of CD152 on the surface of CD4+ T cells after challenge with PN was seen in PN and NA donors but not in CME donors." (PMID 38067164, 2023). "Here, we show that GJExCR treatment reduced the Th2-mediated immune response in OVA-induced allergy, including dampening of IL-4, IL-5, IL-10, IL-13, TNF-α, INF-γ, chemokine, and IgE expression, in both serum and spleens." (PMID 36980282, 2023). "Complications during pregnancy were linked to different pattern of the IFNG, IL5, IL4 and IL10 methylation depending on allergy status." (PMID 37520545, 2023). "Eosinophils are the most potent immune cell during allergy and parasitic infections producing IL-4 and IL-13 cytokines." (PMID 37197738, 2023).
Allergy (continued). "In parallel, the role of IL-4 and IL-13 in the mast cell- and basophil-related context was widely documented by employing numerous human and mice models of allergy." (PMID 36675006, 2023). "TH2 cells (CCR4+ CCR6− CCR10− CXCR3−) orchestrate defense against large extracellular pathogens and helminths by secretion of IL‐4, but are also involved in inflammatory disorders, such as asthma and allergies." (PMID 36740883, 2023). "These EPS inhibited the catalytic activity of hyaluronidase and the overexpression of ear IL-4 mRNA, which eventually led to anti-allergy and anti-inflammatory effects in picryl chloride-induced contact dermatitis." (PMID 36769176, 2023). "IL-4 and IL-13 are cytokines related to type 2 immunity, which mediates the immune response against helminths but is also intrinsically related to allergies." (PMID 37766239, 2023). "High plasma IL-13 and IL-4 in patients with COVID-19 requiring intensive care indicates acute activation of the allergy cytokine pathway in this disease." (PMID 37040185, 2023). "Basophils are known to be involved in allergy through the release of IL-4 and their ability to drive antibody responses." (PMID 38229911, 2023). "A higher methylation of IL4 was positively correlated with the number of family members with allergy." (PMID 37520545, 2023). "IL-4 and IL-13 are members of the Th2-type cytokines and play a critical role in the type II inflammatory response triggered by allergy or parasite infection." (PMID 36985596, 2023). "Estrogen, based on its concentration, was proven to mediate Th1/2 balance and induct proinflammatory cytokines, for example, IL‐4, which is related to an allergic reaction." (PMID 37701228, 2023). "This Th2 subset is responsible for the secretion of interleukin-4 (IL-4) and interleukin-5 (IL-5) cytokines, which play major roles in the regulation of lymphocyte proliferation, and atopic and allergic disease." (PMID 37701007, 2023). "In allergic reactions, allergens activate T cells to differentiate into Th2 cells and secrete IL-4, IL-5, and IL-13, leading to allergen-specific IgE production." (PMID 37101296, 2023). "These functions all suggest that IL-4 plays a significant role in propagating its pathogenesis in the occurrence and development of allergies or tumors." (PMID 36936961, 2023). "We saw a wealth of research into allergic diseases and KD and how these were related to eosinophils, IgE, IgE receptors, and IL-4." (PMID 37508706, 2023). "Several studies have confirmed that higher expression levels of IL-4 and IL-5 will induce allergic diseases in infants." (PMID 36673400, 2023). "Allergic diseases are dominated by systemic type 2 inflammation with overexpression of cytokines such as IL-4 and IL-13, which, in the skin, regulate the epidermal barrier and the effector phase of the immune response." (PMID 37753208, 2023). "It is well known that corticosteroids suppress the synthesis of Th2-derived cytokines (such as IL-4 and IL-13) necessary for the production of IgE, thus contributing to their effectiveness in controlling allergic diseases." (PMID 37514093, 2023). "HRF induces IL-4 and IL-13 production by changing the balance between Th1 and Th2 to a higher Th2 response, which is also a driver of allergic reactions." (PMID 37760889, 2023). "Apart from the release of preformed mediators, the release of de novo synthesized inflammatory mediators such as TNF-α, IL-6, IL-8, and IL-4 by activated MC in a prolonged allergic reaction was well-reported in previous studies." (PMID 37667314, 2023). "On the contrary, many attempts are being made to treat various allergic diseases or/and autoimmune diseases by reducing the level of IL-4 and blocking the binding of IL-4 to its receptor." (PMID 36936961, 2023). "For this reason, many authors considered IL-4 inhibitors key markers for the development of anti-inflammatory and allergy treatments." (PMID 36364783, 2022).
Allergy (continued). "Alleviation of allergy symptoms is due mostly to the manipulation of proinflammatory cytokines secreted by mast cells, and IL-3, IL-4, and IL-13 are regarded as critical therapeutic targets in allergic inflammatory illnesses." (PMID 36142314, 2022). "Type 2 immunity consists of GATA3+ Th2 cells and mediates allergy by producing IgE antibody as well as IL-4, IL-5, and IL-13." (PMID 35484967, 2022). "The results of a study show that intranasal use of SP-D reduced inflammatory symptoms and allergies in mice and also reduced IL-2, IL-4, IL-5, and eosinophil levels." (PMID 35419072, 2022). "Tregs secrete regulatory cytokines such as and IL-10 and TGF-β, which reduce pulmonary eosinophil infiltration, allergy-specific Th2 cytokines (IL-4, IL-5, and IL-13), allergy specific IgG1 and IgE production, allergic rhinitis symptoms, and AHR." (PMID 36556359, 2022). "IL-13 is produced mainly by Th2 cells, shares many physiological functions with IL-4, and is a known factor in allergy pathogenesis." (PMID 36078882, 2022). "This central Th1 cytokine has an inhibitory effect on allergy-mediating Th2 cytokines such as IL-4, IL-5, and IL-13." (PMID 36009677, 2022). "Of course, the leading role is played by the IL-4 and IL-13 genes involved in the development of inflammatory reactions during the exacerbation of allergies, including the work of regulatory T-cells of mucous membranes and skin." (PMID 35629280, 2022). "IL-4 and IL-13 are typical Th 2 cytokines; the former influences the secretion of IgE, while the latter can aggravate allergic reactions." (PMID 35163859, 2022). "When mast cells are activated, the pro-inflammatory cytokines such as IL-4 and IL-13, secreted from Th2 cells, activate B cells and generate an allergic reaction by producing IgE." (PMID 35889810, 2022). "TH2-type CD4+ T cells and the cytokines that produce IL-4, IL-5, and IL-13 are considered major players in the pathophysiology of allergic diseases." (PMID 36364962, 2022). "Dupilumab represents an even more fundamental attack on allergic disease, suppressing IL-4 and IL-13 signaling required for not only IgE production, but the underlying Th2 response driving it." (PMID 36230993, 2022). "In contrast, Th2 cells, which produce IL-4, IL-5, IL-6, IL-9, IL-10, and IL-13, induce strong antibody responses by B cells, induce eosinophil activation, and are responsible for allergic reactions." (PMID 35646978, 2022). "Firstly, increasing IL-4 can suppress CMI and changes the balance of Th1/Th2 toward Th2 responses in favour of increasing allergic diseases and susceptibility to intracellular microbes and cancer." (PMID 36114367, 2022). "PPAR-γ agonists reduced the expression of TNF-α and IL-4 through down-regulation of NF-κB activation in mast-cell-related allergic diseases." (PMID 35807237, 2022). "Decrease in different cytokines levels (including IL-4) and limiting iNOS production of NO is observed after treatment of allergic diseases with antyhistamines." (PMID 35160089, 2022). "In an allergic reaction, the immune response shifts to Th2 type, and activated Th2 cells can produce cytokines, such as IL-4." (PMID 36317119, 2022). "We provide evidence that this is being driven by type 2 inflammation, demonstrated by IL-4/IL-13 and Th2 gene expression signatures and clinical allergic disease that dramatically responds to Jakinib therapy." (PMID 36546480, 2022). "As an important Th2 cytokine, IL-4 stimulates B cell differentiation and IgE production, inducing the degranulation of mast cells and aggravating allergic reactions." (PMID 35681291, 2022). "As the overproduction of IL-4 plays a central role in the pathogenesis of allergic diseases, modulation of IL-4 expression can mitigate disorders involving Th2 polarization." (PMID 35910793, 2022). "Subgroup analyses showed that higher Il-4 and Il-13 transcripts in cord blood CD4+ T-cells were associated with an increased risk of allergic diseases in children of the HC group." (PMID 35745240, 2022).